E2F4 (E2F transcription factor 4)
Diseases named in the same sentence as E2F4 in open-access papers (continued):
Sharing a sentence is not in itself a finding about the gene and the disease.
prostate carcinoma (13 papers, 2017 to 2025). A carcinoma that arises from epithelial cells of the prostate gland. "Therefore, down-regulation of E2F4 in prostate cancer could lead to an increase in mutations and tumor progression and proliferation." (PMID 38173042, 2024). "E2F4 is known to repress Bub3 and Pttg1, two important mitotic genes, in prostate cancer and play a crucial role in G2 arrest." (PMID 38173042, 2024). "E2F4 is involved in the carcinogenesis of skin tumors, gastrointestinal tumors, and prostate cancer 21,22." (PMID 34335934, 2021). "The changes in the levels of E2F4 in prostate cancer were thought to promote increased sensitivity, via inactivation of E2F4 by siRNA, and prevent ionising radiation-induced apoptosis." (PMID 30487158, 2018). "Notably, the androgen receptor-independent transactivation of KHDC4 and TRAF2 by E2F4 was demonstrated using multiple prostate cancer cell lines and further validated through clinically relevant transcriptome datasets." (PMID 40560737, 2025). "Inositol hexaphosphate (IP6) inhibits growth, and induces G1 arrest and apoptotic death of prostate carcinoma DU145 cells via decreasing the level of E2F4 as well as via increasing binding of E2F4 with pRb/p107 and pRb2/p130, thus modulating CDKI-CDK-cyclin and pRb-related protein-E2F complexes." (PMID 33390186, 2021). "In short, few studies have focused on the function of these three E2Fs in PCa, and the roles of E2F4, E2F7, and E2F8 in prostate cancer remain to be explored." (PMID 35531101, 2022). "Similar to E2F2 and E2F4 mentioned previously, E2F6 has been reported in few prostate cancer studies." (PMID 35531101, 2022). "In earlier investigations it has been demonstrated that E2F4 mutations had been associated with GACs, ulcerative colitis-associated neoplasms, colorectal carcinomas, endometrial cancers and prostatic carcinomas and that E2F4 expression did not assist in apoptosis." (PMID 30487158, 2018). "Consequently, E2F1, E2F4, and E2F5 had negative correlations with DBNDD1 expression in normal prostate tissues but positive correlations in prostate carcinoma tissues." (PMID 37569304, 2023).
colorectal cancer (12 papers, 2013 to 2026). A primary or metastatic malignant neoplasm that affects the colon or rectum. "E2F4 frameshift mutations have previously been found among MSI-H colorectal cancers." (PMID 25836926, 2015). "Western blotting, q-PCR and immunohistochemistry et, al. were used to detect the level of MNX1 in patients with colorectal cancer, and Chip-PCR was used to detect the targeted binding ability of E2F4 and MNX1." (PMID 37779874, 2023). "Cell cycle genes have been revealed to be evolutionarily conserved targets of E2F4, and E2F4 expression is required for cell cycle progression of colorectal cancer cells." (PMID 35101047, 2022). "it is also estimated that E2F4 acts as bridging genes in the process of colorectal cancer liver metastasis." (PMID 33613768, 2021). "In this respect, decreased expression of E2F4 by RNA interference reduced the proliferation rate of normal intestinal epithelial crypt cells and colorectal cancer cells in culture." (PMID 23919615, 2013). "Accordingly, we have previously shown that E2F4 expression is necessary for both anchorage-dependent and independent growth of colorectal cancer cells." (PMID 23919615, 2013). "Results of the present study demonstrate that E2F4 protein levels were significantly enhanced in human adenomas, at an early stage of colorectal cancer." (PMID 23919615, 2013). "E2F4 accelerates the progression of colorectal cancer by promoting AGAP2-AS1 expression." (PMID 37349788, 2023). "Expansion of CAG repeats in the E2F4 coding sequence is also frequent in tumors with genomic instability such as colorectal carcinomas, and could be oncogenic by stabilizing E2F459." (PMID 31270324, 2019). "Furthermore, a lncRNA E2F4 transcription was directly activated by the β-catenin that accumulated in the nucleus in colorectal cancers, resulting in cancer progression." (PMID 26868975, 2016). "E2F4 protein expression is up-regulated in human colorectal cancers." (PMID 23919615, 2013). "Therefore, we found E2F4 upregulation in colorectal cancer tissues and CRC cell lines." (PMID 37779874, 2023). "In conclusion, we proposed that E2F4 may act as a transcriptional regulator, activating MNX1 to induce colorectal cancer development." (PMID 37779874, 2023).
hepatocellular carcinoma (11 papers, 2011 to 2025). A malignant tumor that arises from hepatocytes. "E2F4 expression was found to be significantly associated with immune cell infiltration among lymphoma, pancreatic adenocarcinoma, and hepatocellular carcinoma." (PMID 36567912, 2022). "In hepatocellular carcinoma, E2F4 promotes the proliferation, migration and invasion of hepatocellular carcinoma cells by upregulating CDCA3." (PMID 37349788, 2023). "E2F4 promotes proliferation and cell cycle progression in hepatocellular carcinoma cells by up-regulating CDCA3 expression." (PMID 34905505, 2021). "In order to assess the differences in binding among different human tissues, we compared our E2F4 ChIP-seq data in adipocytes with the published E2F4 ChIP-chip data in human liver, pancreatic islets, pancreatic acinar tissues and the liver carcinoma cell line HepG2." (PMID 21655096, 2011). "There are limited studies on the role of E2F4 in hepatocellular carcinoma (HCC)." (PMID 34335934, 2021). "Two target genes of E2F4, CDK1 and TP73 were also involved in liver cancer development and proposed as prognostic marker of poor patient survival prognosis in hepatocellular carcinoma." (PMID 28347313, 2017). "Interestingly, the mining of sequencing data of a cohort of patients with liver hepatocellular carcinoma (LIHC) included in The Cancer Genome Atlas (TCGA) shows that YY1, E2F4, and NRF1 expressions were significantly upregulated in the liver of HCC patients." (PMID 37627157, 2023).
colon cancer (10 papers, 2014 to 2025). "E2F4 over-expression was associated with breast and colon cancers; its mutation was associated with endometrial, prostate, colorectal, gastric, and ulcerative colitis-associated neoplasm; and its amplification was associated with bladder cancer." (PMID 30020984, 2018). "Another study showed that E2F4-specific knockout by lentivirus infection reduced G1/S transition and proliferation rates of normal human intestinal epithelial and colon cancer cells." (PMID 35840663, 2022). "The Kaplan–Meier showed that E2F3 and E2F4 displayed significantly correlation with the overall survival of patients with colon cancer." (PMID 32117628, 2020). "Studies have shown that over-expressed E2F4 is related to colon cancer, kidney cancer, and lung cancer." (PMID 33604289, 2020). "E2F4 as well as its target cyclin A were significantly up-regulated and mostly nuclear in human colon tumor cells compared with the corresponding benign epithelium." (PMID 32117628, 2020). "E2F4 iRASs were calculated for samples in bladder cancer, colon cancer, NSCLC, glioblastoma, AML, and Burkitt’s lymphoma datasets and used in conjunction with the available survival data to generate Kaplan-Meier plots." (PMID 25440089, 2014). "In colon cancer, although the survival curves for E2F4 iRAS >0 group and iRAS <0 groups are fairly separated, the statistical difference is only moderately significant (P = 0.04)." (PMID 25440089, 2014). "E2F4 is a mechanistic regulator of colon cancer sensitivity to irinotecan." (PMID 39896677, 2025). "In another study, chlorophyllin treatment has been reported to cause cell cycle arrest in HCT116 colon cancer cells through the increased expression of E2F1 and E2F4 transcription factors inhibiting the G1/S checkpoint step, which is an important cell cycle checkpoint." (PMID 40014124, 2025). "Additionally, E2F3, E2F4, E2F7 and E2F8 were significantly associated with the stages of colon cancer." (PMID 32117628, 2020). "The mutations of E2F4 also enhanced the capacity of colon cancer cells to grow without anchorage, therefore giving rise to tumor progression." (PMID 32117628, 2020). "In addition, the expression of E2F3, E2F4, E2F7 and E2F8 were significantly associated with tumor stages and overall survival of the patients with colon cancer, suggesting that they may serve as potential therapeutic targets for colon cancer." (PMID 32117628, 2020). "Our study implied that E2F3, E2F4, E2F7 and E2F8 are potential targets of precision therapy for patients with colon cancer while E2F1, E2F2, E3F3, E2F5, E2F7 and E2F8 are potential biomarkers for the diagnosis of colon cancer." (PMID 32117628, 2020). "The results demonstrated that the expression levels of E2F3, E2F4, E2F7 and E2F8 displayed significant correlation with the tumor stage in patients with colon cancer while other members in E2F family in normal group and tumor group did not significantly differ." (PMID 32117628, 2020). "Our results show that E2F4 was significantly correlated with survival time in bladder cancer, glioblastoma, and colon cancer, but not in NSCLC, AML or Burkitt’s lymphoma." (PMID 25440089, 2014).
lung carcinoma (9 papers, 2010 to 2024). "In addition, the E2F4/p130 pathway has been implicated in the growth and progression of lung cancer." (PMID 20421925, 2010). "Herein, we found that knockdown of USP24 by shUSP24 or targeting USP24 by the USP24 inhibitor USP24-i in A549-T24 and PC9-GR drug-resistant lung cancer cell lines increased the LC3 levels but decreased the E2F4 levels." (PMID 38491202, 2024). "In this study, we found that targeting USP24 by the specific USP24 inhibitors, USP24-i and its analogues, dramatically activated autophagy in the interphase and mitotic periods of lung cancer cells by inhibiting E2F4 and TRAF6, respectively." (PMID 38491202, 2024). "Analysis of our gene expression profiling studies and chromatin occupancy in mouse and human lung cancer models reveals a strong enrichment for E2F4 and E2F6 targets amongst genes bound by and regulated by MGA." (PMID 34236315, 2021). "The most enriched GSEA terms were reactome cell cycle, marson bound by E2F4 unstimulated, gobert oligodendrocyte differentiation up and shedden lung cancer poor survival A6." (PMID 31781497, 2019). "Interestingly, in the present study, we identified that E2F2, E2F3, and E2F4 were not essential genes in lung cancer cells from Project Achilles." (PMID 33924966, 2021). "In this study, several cancer-related proteins (Bax, p300, E2F4 and securin) have been proven to be substrates of ubiquitin-specific peptidase 24 (USP24), and relevance has been shown between USP24 and its substrates in samples from clinical lung cancer patients." (PMID 27991932, 2017).
glioma (8 papers, 2009 to 2025). A benign or malignant brain and spinal cord tumor that arises from glial cells (astrocytes, oligodendrocytes, ependymal cells). "In recurrent gliomas, E2F4 showed a significant positive correlation with the expression of MCM8, DBF4 and CDKN2C." (PMID 37349788, 2023). "Patients with WHO grade III glioma or WHO grade IV primary glioma with high E2F4 expression have a poor overall survival." (PMID 37349788, 2023). "We found that E2F4 expression in GSCs was significantly higher than that in NSCs, and it was identified as an unfavorable prognostic factor for glioma patients." (PMID 37349788, 2023). "The expression of MCM8, DBF4 and CDKN2C displayed a significant positive correlation with E2F4 expression in both primary and recurrent glioma tissues." (PMID 37349788, 2023). "Since E2Fs bind to similar DNA binding sequences, we conducted correlative analysis of H2AZ2 with E2F1 and E2F4 in TCGA glioma." (PMID 35058574, 2022). "Curiously, FOXM1 and E2F4 were enriched only in glioma tumors, which deserves further exploration in the next section." (PMID 32807122, 2020). "The role and mechanism of E2F4 in glioma are still not well understood." (PMID 37349788, 2023). "From our ATAC-Seq analysis of H2AZ2 KD cells, we searched the ReMap datasets and identified E2F4 among the top glioma-relevant transcriptional regulators whose promoter accessibility may be altered in H2AZ2 depleted cells." (PMID 35058574, 2022). "Furthermore, the higher WHO glioma grading, the higher the expression of E2F4, suggesting that E2F4 might play a role in the malignant progression of gliomas." (PMID 37349788, 2023). "Moreover, E2F4 expression is increasing with the WHO glioma grade." (PMID 37349788, 2023). "Interestingly, we found that AMPK scores were significantly negatively correlated with TF expression levels in glioma: E2F4 (rho = − 0.48, P < 0.0001), EZH2 (rho = − 0.57, P < 0.0001), FOXM1 (rho = − 0.49, P < 0.0001), SMAD4 (rho = − 0.18, P < 0.0001) and SUZ12 (rho = − 0.23, P < 0.0001)." (PMID 32807122, 2020). "Additionally, TFs FOXM1 and E2F4 were identified to be enriched only in glioma tumors." (PMID 32807122, 2020). "The correlation between E2F4 and LIN9, MCM8, CEP72, POLA1, DBF4, NDE1 or CDKN2C expression in glioma tissues was analyzed using CGGA." (PMID 37349788, 2023). "The findings presented herein indicated that E2F4 and MCM8 represent promising therapeutic targets for the treatment of gliomas." (PMID 37349788, 2023). "There was a strong positive correlation between E2F4 expression and the expression of MCM8, DBF4 and CDKN2C in both primary and recurrent glioma tissues, with the most prominent impact on patient prognosis being observed for MCM8." (PMID 37349788, 2023). "We observed that TWEAK treatment increased nuclear E2F4 and E2F5 protein levels in glioma cells, with E2F4 having greater nuclear translocation in BT25 cells and E2F5 in BT114 cells." (PMID 36945490, 2023). "Our analysis revealed a significant positive correlation between E2F4 and MCM8, POLA1, DBF4, NDE1 or CDKN2C expression in primary gliomas." (PMID 37349788, 2023). "The roles and mechanisms of E2F4 and MCM8 in maintaining the characteristics of GSCs and regulating gliomas progression still needs to be further explored at the in vivo level." (PMID 37349788, 2023). "Dlk1 expression is increased in gliomas and over-expression in transfected cells promotes cell proliferation by inducing the expression of cyclin D1, CDK2, and E2F4." (PMID 19331679, 2009). "Furthermore, we demonstrate that the E2F transcription factors E2F4 and E2F5 directly regulate NIK transcription and are required to promote glioma cell invasion in response to TWEAK." (PMID 36945490, 2023).
glioma (continued). "As this analysis has shown that all of these processes are co-ordinately regulated, the identification of two transcription factors that are associated with all or almost all of these modules suggests that both E2F4 and ETS1 play a significant role in the pathogenesis of glioma." (PMID 24523864, 2014). "There was a significant association between H2AZ2 and E2F1 (but not E2F4), suggesting that E2F1 may be co-expressed with H2AZ2 in glioma." (PMID 35058574, 2022).
cervical cancer (7 papers, 2015 to 2022). A primary or metastatic malignant neoplasm involving the cervix. "Although the association of cervical cancer with E2F4 and ETS1 was clearly identified, the relationship with CUTL1 was not clearly specified." (PMID 30020984, 2018). "Then, cervical cancer cells were treated with HAND2‐AS1 or si‐E2F4 RNA, or C16orf74, after which the proliferation, colony formation, migration and invasion were detected." (PMID 32314545, 2020). "Overall, our findings demonstrate that HAND2‐AS1 activated E2F4 to down‐regulate C16orf74 in cervical cancer." (PMID 32314545, 2020). "HAND2‐AS1 attenuated cell proliferation, migration, invasion and tumorigenesis of cervical cancer by down‐regulating C16orf74 expression through recruiting E2F4." (PMID 32314545, 2020). "Our findings indicated that HAND2‐AS1 suppressed the cell proliferation, migration, invasion and tumorigenesis of cervical cancer by recruiting E2F4 to down‐regulate C16orf74 expression." (PMID 32314545, 2020). "E2F4 was identified to be critical in the regulation of cell progression in various cancers and found to be related to cervical cancer." (PMID 32314545, 2020). "In conclusion, this study provided evidence on the inhibitory effect of HAND2‐AS1 on the development of cervical cancer through the suppression of C16orf74 expression by recruiting transcription factor E2F4." (PMID 32314545, 2020). "The transcriptional expression of the core genes of cervical cancer was controlled by three TFs: E2F4, ETS1, and CUTL1." (PMID 30020984, 2018). "The lncRNA‐trans‐regulation network analysis suggested that E2F4 may be the core transcription factor in the lncRNA‐TF regulatory network in cervical cancer." (PMID 35262965, 2022). "lncRNA‐trans‐advanced analysis suggested that E2F4 may be the core transcription factor in the lncRNA‐TF regulatory network in cervical cancer." (PMID 35262965, 2022). "The lncRNA‐TF regulatory network plays an important role in the occurrence and progression of cervical cancer, and E2F4 may be a critical transcription factor in the regulatory network." (PMID 35262965, 2022). "Lastly, HAND2‐AS1/E2F4/C16orf74 modulated the tumorigenesis of cervical cancer in nude mice." (PMID 32314545, 2020). "In addition, we observed that the ability of colony formation in cervical cancer cells was increased upon E2F4 silencing or C16orf74 overexpression in the presence of HAND2‐AS1 overexpression (P < .05)." (PMID 32314545, 2020). "In addition, cell migration and invasion were also enhanced following E2F4 silencing or C16orf74 overexpression treatment in cervical cancer cell overexpression of HAND2‐AS1 (P < .05)." (PMID 32314545, 2020). "Next, we investigated whether HAND2‐AS1/E2F4/C16orf74 regulated the malignant characteristic of cervical cancer cells." (PMID 32314545, 2020). "Furthermore, the effect of HAND2‐AS1/E2F4/C16orf74 axis on the progression of cervical cancer was explored." (PMID 32314545, 2020). "We found that upon HAND2‐AS1 overexpression, E2F4 silencing or C16orf74 overexpression could promote the proliferation of cervical cancer cells (P < .05)." (PMID 32314545, 2020). "Finally, the tumorigenesis of cervical cancer cells was measured in nude mice with altered HAND2‐AS1/E2F4/C16orf74 expression." (PMID 32314545, 2020). "Here, the purpose of this study was to identify whether lncRNA heart‐ and neural crest derivative‐expressed 2‐antisense RNA 1 (HAND2‐AS1) affect the development of cervical cancer through regulation of chromosome 16 open reading frame 74 (C16orf74) by mediating a transcription factor E2F4." (PMID 32314545, 2020). "Furthermore, Western blot analysis was used to detect the expression of N‐cadherin, vimentin, MMP‐2 and MMP‐9 in cervical cancer cells, the results of which showed an up‐regulation in these proteins upon E2F4 silencing or C16orf74 overexpression in the presence of HAND2‐AS1 overexpression (P < .05)." (PMID 32314545, 2020).